IL10 (interleukin 10)
Diseases named in the same sentence as IL10 in open-access papers (continued):
Sharing a sentence is not in itself a finding about the gene and the disease.
cancer (continued). "Whereas the role of IL10 on cancer growth may be ambiguous we expect an overall beneficial impact of IL7/12 engineered MSC on a CAR T cell attack." (PMID 32260097, 2020). "In particular, IFNγ and IL-10 have opposite roles in cancer." (PMID 32733470, 2020). "In the neoplastic process, production of IL-10 may result in a different outcome depending on the type of cancer, and its source is usually the same cancer cell or Treg." (PMID 32488850, 2020). "The systemic inflammatory response from cancer cells promotes the infiltration of neutrophils, which benefits cancer progression via secreting interleukin-2 (IL-2), interleukin-6 (IL-6), interleukin-10 (IL-10), tumor necrosis factor α (TNF-α) and vascular endothelia growth factor (VEGF)." (PMID 32510138, 2020). "The presence of IL-10 in conjunction with MC chemokines and alarmins such as IL-33 explains the pro-cancer, pro-inflammatory role MCs can play in certain cancers; in the context of small bowel cancers, MC protease expression resembled MMCs but included CTMC-related mast cell proteases too." (PMID 32098318, 2020). "Although widely considered as an anti-inflammatory cytokine, IL-10 could also induce the cytotoxicity of CD8+ T cells in an immune response to cancer." (PMID 32348468, 2020). "Despite it, IL-10/IL-10R complex is still an attractive target for cancer immune therapy." (PMID 32670290, 2020). "In contrast, the accumulation of Tregs in cancer tissues requires high IL-10 expression." (PMID 32547401, 2020). "Therefore, butyrate promotes the integrity of gut epithelial tight junctions as well as increases the release of the anti-inflammatory cytokine IL-10, that protects against cancer formation." (PMID 32947866, 2020). "IL-10 in TME is primarily secreted by cancer cells, TAMs, natural killer cells (NK) and CD4+ Tregs." (PMID 32117960, 2020). "Through IL-10-dependent mechanism, an enhancement of cytokine production that was associated with T helper (Th2 and Th17 cells) (e.g., IL-2, -4, -6, -10, -17A and IFN-α and -γ) were observed for a glucan product of C. versicolor in cancer-bearing mice." (PMID 32466253, 2020). "Moreover, exosomes also induce the expression of IL-10 in macrophages and PD-L1 in cancer cells, so resulting in the promotion of an immunosuppressive environment." (PMID 32344813, 2020). "IL-10 was proven to be a potent anti-inflammatory cytokine, and is mainly produced by Treg cells but in also produced by other immune cells such as B cells, TAMs, mast cells, granulocytes, and dendritic cells as well as cancer cells themselves." (PMID 32225066, 2020). "We examined the effect of IL10 on PCa cell lines representing various stages of cancer development." (PMID 32802517, 2020). "PD-L1 and IL10 were positively correlated in carcinoma tissues and adjacent tissues." (PMID 32724815, 2020). "Several inflammatory mediators, such as TNF-α, IL-6, and IL-10, might have an effect in the initiation and progression of cancer, so the inflammatory microenvironment can be relate to the tumorigenesis of liver." (PMID 31340754, 2019). "Moreover, the expression of Hsp27 induces monocyte to produce IL-10, which is a strong inhibitor of the Th1 response and is constantly found to be elevated in human cancers." (PMID 31827382, 2019). "IL-10 is a pleotropic cytokine with both anti-cancer and anti-inflammatory potential." (PMID 31649244, 2019). "Previous work clearly demonstrated that IL-6 could promote intestinal inflammation and cancer development, whereas interleukin-10 (IL-10) coordinated regulatory T cells to suppress inflammation and carcinogenesis." (PMID 30944705, 2019). "The results of the present study demonstrated that ESTIMATE algorithm-based stromal and immune scores may be a credible indicator of cancer prognosis and IL10 along with XCR1 may be a potential key regulator for the TME of ccRCC." (PMID 31781309, 2019).
cancer (continued). "Moreover, metformin induces anti-inflammatory property that inhibits DSS-induced IκB kinase activation and reduced colitic cancer development in IL-10−/− mice by augmenting AMPK activation in the intestinal epithelial cells." (PMID 31831021, 2019). "IL-10 has been shown to increase the expression of Mgat5, a glycosyltransferase that increases branching of glycoproteins on the surface of CD8+ T cells and has been associated with the progression of cancer." (PMID 30894857, 2019). "Indeed, macrophages exposed to IL-10 are known to polarize into M2 phenotypes under sustained IL-10 exposure, and CSCs from ovarian and other cancers can induce pro-tumoral macrophage phenotypes through other pathways including NF-kB." (PMID 31324218, 2019). "Higher baseline levels of IL-8 and IL-10 were also associated with cancer mortality overall but not in race stratified models." (PMID 31448052, 2019). "Hence, IL-10 plays a paradoxical role in cancer immunotherapy through activation or inhibition of IL-10 signaling." (PMID 32010123, 2019). "Furthermore, IL-10 treatment increases serum levels of pro-inflammatory cytokines IL-18 and IFNγ as well as FasL in cancer patients and the induced cytokine levels are strongly correlated with clinical responses." (PMID 31379815, 2019). "Moreover, GSK-J4 reduced IFN-γ, TNFα, granulocyte–macrophage colony-stimulating factor (GM-CSF), and interleukin-10 levels in cytokine-stimulated NK cells while sparing their cytotoxic killing activity against cancer cells." (PMID 29301935, 2018). "In the immune microenvironment of EC, cancer cells can secrete many immunosuppressive molecules, such as IL-10, TGF-β, and indoleamine 2,3-dioxygenase that could suppress the differentiation, maturation, and function of DCs and effector T cells." (PMID 29435196, 2018). "However, it has been shown recently that IL-10 plays also a major role as an immune-activating cytokine in cancer immunotherapy." (PMID 30108590, 2018). "IL10 production is a characteristic feature for Cancer detection." (PMID 30183728, 2018). "However, B cells not only have regulatory effects on IL-10 secretion but also generate IL-35, yet studies focusing on this phenomenon in cancer patients are very rare." (PMID 29742730, 2018). "IL-10 is an anti-inflammatory cytokine that modulates cytokine synthesis and exerts effects on resident and circulating immune cells, suppressing the immune system; however, their role in cancer remains controversial." (PMID 30532757, 2018). "Moreover, the results showed a significant positive correlation between the concentration of LC3B+ autophagosomes and the expression of PD-L1 and IL-10 in matched monocytes from effusions or ascites of cancer patients." (PMID 30563569, 2018). "The controversial role of IL-10 in cancer development is still a subject of discussion." (PMID 29954431, 2018). "Several carcinomas and cancer cell lines produce IL‐10 and FoxP3, indicating that tumors may promote a biased Th2 response promoting IgG4, but limiting immune responses and enabling the escape from immune clearance." (PMID 29164823, 2018). "IL-10 has been described in many cancer patients as a poor prognostic factor." (PMID 30233565, 2018). "Indeed, preclinical data regarding IL-10 blockade has demonstrated an enhancement of vaccine immunogenicity, not only in the cancer setting but also in other models." (PMID 30233565, 2018). "Little is known about the effect of IL-10 on human cancer cell line migration." (PMID 29256156, 2018). "In addition, PD-L1 and IL-10 expression in matched monocytes, which were collected from effusions or ascites of cancer patients, was correlated with the levels of LC3B+ EVs in the same cohort." (PMID 30563569, 2018). "Concentrations of potential cancer markers (sHLA-G, IL-10 and TNF-alpha) in body fluids (serum and peritoneal fluid) are not stable, which may be associated with both their sources and natural history of the disease." (PMID 28376925, 2017).
cancer (continued). "PD-L1 expression in macrophages is induced by cancer-derived factors, and macrophage-derived interleukin 10 is involved in the induction of PD-L1 expression, suggesting that cell-cell interaction with cancer cells is necessary for PD-L1 expression in macrophages." (PMID 28086852, 2017). "Our results indicate that immunization with an IL-10 inhibitor may facilitate the generation of safe, effective therapeutic vaccines against chronic viral infection and cancer." (PMID 28810829, 2017). "Patients with active cancer also exhibited higher baseline lactate levels (p = 0.038), and higher baseline plasma interleukin (IL)-10 levels (p = 0.040), higher trend of granulocyte colony-stimulating factor (G-CSF) (p = 0.004) compared to patients without active cancer." (PMID 28692671, 2017). "Another meta-analysis including 15,942 cases and 22,336 controls investigated IL-10 -819C/T polymorphism and cancer risk, without finding any significant association between this polymorphism and overall cancer risk." (PMID 28977953, 2017). "Furthermore, metformin treated cancer cells displayed inhibited secretion of IL-4, IL-10 and IL-13; cytokines important for inducing M2 macrophages." (PMID 28157701, 2017). "Therefore, the blockade of several repressive pathways, such as TGF-β, PD-1, or IL-10, can enhance the number of CTLs and efficacious functions to protect against cancer and chronic infections." (PMID 29163789, 2017). "IL-10 is an antihyperalgesic cytokine in inflammatory, neuropathic, and cancer pain models." (PMID 28589150, 2017). "For example, several pro-inflammatory cytokines, including interferon gamma (IFN-γ), tumor necrosis factor alpha (TNF-α), transforming growth factor beta (TGF-β), and interleukin-10 (IL-10), have been shown to contribute to both the initiation and development of cancer." (PMID 29268703, 2017). "IL-1β, IL-4, TGF-β1a, and IL-10 mRNA levels were unaffected by cancer cell EVs." (PMID 28947958, 2017). "These contrary findings may be due to the intrinsically pleiotropic biological activity of IL-10 and the variability of cancer models, or possibly genetic factors between different races." (PMID 27811370, 2016). "Furthermore, PTEN can promote host immune response against cancer cells by repressing the expression of immunosuppressive cytokines IL-10, IL-6, and VEGF and programmed cell death 1 ligand (PD-L1) in a PI3K/AKT pathway-dependent manner." (PMID 27391071, 2016). "The role of IL10 in the tumorigenesis of various cancer types is still controversial." (PMID 26956044, 2016). "Cancer cells often secrete MΦ2-type cytokines such as IL-10, CCL2, CXCL12, and VEGF." (PMID 27231721, 2016). "Further basic and clinical investigation may be warranted and needed to evaluate the hypothesis that IL-10 could be druggable in the curing of cancers on systemic as well as cellular level." (PMID 27765933, 2016). "The present study substantially demonstrates that the FcγRIIlow/− activated B cells in a cancer environment produce protumorigenic IL-10 to suppress cytotoxic T-cell function, representing a link between immune activation and immunosuppression in the cancer environment." (PMID 27853178, 2016). "In addition, DCs tend to adhere more to MUC1-STn+ cancer cells and this contact inhibits DC maturation, inducing them to produce IL-10 and reducing their ability to trigger the protective T helper 1 (Th1) response." (PMID 27754373, 2016). "The influence of IL-10 on more severe cancer disease is explained by antagonistic effect of IL-10 on the formation of pro-inflammatory cytokines (IL-6, TNF, IL-1α, IL-1β, IL-12) and inhibition of the inflammatory response, which plays an important role in the development of cancer." (PMID 27547238, 2016). "In addition to impairing the activation of cytotoxic T lymphocytes (CTLs) and Th1 CD4+ cells, IL10 inhibits the cytolytic activity of natural killer cells and CTLs, which are responsible for the immune surveillance of cancer." (PMID 26956044, 2016).
cancer (continued). "Serum levels of IL-10 in patients from the control group was 81.8 % and 96.8 % in cancer subjects." (PMID 26905729, 2016). "This role of IL-10 fostered the assumption that it undermines the immune response to cancer." (PMID 27600085, 2016). "IL-10 is a well-known immune suppressive cytokine produced during cancer progression." (PMID 26840567, 2016). "High level of serum IL–10 showed poor prognosis of cancer patients, suggesting IL–10 antagonist may be a novel therapeutic technique for clinical treatment of cancer patients." (PMID 26440936, 2015). "Contradictory observations for the role of IL-10 in cancer have been reported." (PMID 26528857, 2015). "Additionally, our findings present statistical evidence for the clinical application of IL–10 antagonists in cancer therapy." (PMID 26440936, 2015). "High expression of serous IL–10 leads to an adverse survival in most types of cancer." (PMID 26440936, 2015). "The IL-10 network is probably the most relevant link between cancer and inflammation." (PMID 26457674, 2015). "In addition to IL-10-mediated anti-inflammation, targeting to FcγRIIA and other FcγRs has also been developed to treat inflammation and cancer." (PMID 25896516, 2015). "Both human recombined IL–10 and IL–10 antagonist have been launched for cancer therapy." (PMID 26440936, 2015). "Results showed that IL–10 overexpression was associated with worse 1-year DFS (OR = 3.34, 95% CI = 1.40 to 7.94, P = 0.0006) and worse 2-year DFS (OR = 3.91, 95% CI = 1.79 to 8.53, P = 0.0006) of cancer." (PMID 26440936, 2015). "Indeed, extracellular signaling of FGF10, VEGFC, IL10 and TNFα of AMSCs was dramatically induced when they were co-cultured with cancer cells, and these molecules are suggested to have a direct or indirect impact on Wnt signaling pathway." (PMID 26060426, 2015). "Nowadays, deep insight into the controversial functions of IL–10 in cancer is urgently needed." (PMID 26440936, 2015). "Interestingly, in the present work we demonstrate that these signalling pathways are being similarly induced by LPS- and IL-10-stimulated macrophages, despite their distinct effects on cancer cell invasion and motility." (PMID 26043921, 2015). "In the case of IL-10, several studies have reported that patients with cancer present high IL-10 concentrations, which may be the reason why its increment has been correlated with a poor prognosis." (PMID 25759825, 2014). "The concentration of plasma IL-10 was found to increase with the cancer staging." (PMID 24765208, 2014). "Inflammation-activated cancer cells-driven products could induce the high expression of cytoplasmic IL-10 in B cells." (PMID 25381811, 2014). "Importantly, we demonstrated that even in myDC from advanced cancer patients that are severely impaired in their ability to produce IL-12, p38i restores secretion to normal levels whilst suppressing IL-10." (PMID 23901045, 2014). "Another study analyzed the interaction of MDSCs with macrophages in a mouse cancer model and showed that, through IL-10 secretion, MDSCs also induced a type-2 polarization of macrophages which is characterized by a decrease of IL-12 secretion and that promotes tumor growth." (PMID 24995313, 2014). "The IL-10 network is among the most important paths linking cancer and inflammation." (PMID 25056661, 2014). "As in cancers, HLA-G expression is upregulated in infectious diseases, in response to changes in the cytokine microenvironment, relating principally to increases in the levels of IL-10 and interferons." (PMID 24839609, 2014). "The elevation of circulating IL-10 had been previously reported in some cancer patients." (PMID 24520352, 2014). "Furthermore our report is also inconsistent with other cancer studies that reported a higher IL-12, IL-10 levels with worse survival." (PMID 25177683, 2014).
cancer (continued). "Although Foxp3 is a master transcription factor for Treg cells, Foxp3 and IL-10 are expressed in several carcinoma tissues and cultured cancer cell lines, suggesting that cancer cells induce the Treg cell-like immunoregulatory milieu to evade immunosurveillance." (PMID 25132998, 2014). "The IL10/Nox1dKO model will help testing the preventive and curative effect, the long-term efficacy in maintaining remission, and probably the long-term properties in preventing cancer of current and future molecules." (PMID 25014110, 2014). "In addition, the structural data of protein complexes suggest how oncogenic mutations influence the interactions and explain their potential impact on IL-10 signaling in cancer and inflammation." (PMID 25056661, 2014). "Numerous studies have investigated the association between IL-10 promoter polymorphisms and the susceptibility to various types of cancers, but this association has not been examined in LSCC." (PMID 24765208, 2014). "Concomitant expressions of IL-17A, with or without IFN-γ, pro-angiogenic VEGF, pro-survival BCL2A1 and suppressive IL-10 or free radical peroxynitrite may indicate that IL-17A strongly supports cancer development." (PMID 23441221, 2013). "In cancer, considered to be a Th2-dominant disease with excess of IL-4, IL-5, IL-10, and TGF-β production, a therapeutically driven shift back toward the Th1 profile is of interest, as it might correlate with immune and perhaps clinical recovery." (PMID 23730621, 2013). "In addition we now show an increased frequency of the CD14+ DDC subset among DC migrating from IL-10- and cancer-conditioned skin." (PMID 23875023, 2013). "Owing to the vital role of IL-10 in the immune response and the link between defective IL-10 production and certain autoimmune and inflammatory diseases as well as cancer, an understanding of the molecular and cellular mechanisms that regulate this cytokine is critical." (PMID 24330710, 2013). "Several studies support the view that IL-10 may diminish the immune response against cancer by directly inhibiting cell activation of select human T cell subpopulations." (PMID 23533029, 2013). "IL-10 is produced mostly by macrophages and myeloid DCs and is generally regarded as an anti-inflammatory cytokine exerting several effects in immunomodulation of the cancer microenvironment and cancer progression." (PMID 23616009, 2013). "In their study, commensal E. coli NC101 promoted CRC in AOM treated IL-10-deficient mice while a deletion of the bacterium's polyketide synthase island decreased cancer multiplicity and invasion without affecting the inflammation in the model." (PMID 24039130, 2013). "The elevated expression of IL-10 may allow for virus persistency, the transformation of cervical epithelial cells, and consequently cancer development." (PMID 22220169, 2012). "Whether IL-10-819 SNP may also influence cancer angiogenesis is worthy of further investigating in the future." (PMID 22436502, 2012). "While several of the molecules associated with regulatory DC function (IL-10, TGFβ, IDO, PGE2, and CD25) have been elucidated and observed in numerous cancer entities and chronic infections, the molecular mechanisms reprogramming DC to become DCreg are still poorly understood." (PMID 22969767, 2012). "Similarly, Raw264.7 monocyte/macrophages are only polarized to produce IL-10 following co-culture with irradiated cancer cells." (PMID 22761754, 2012). "Co-culture with irradiated cancer cells increased IL-10 secretion following LPS stimulation." (PMID 22761754, 2012). "We previously reported IFN-κ and IL-10 downregulation in dysplastic and carcinoma epithelium." (PMID 22013487, 2012). "However, further work elucidating potentialimmunomodulatory roles of B cells and other immune cells in cancer, including theproduction of IL-10 by B cell population subsets, merits consideration." (PMID 21559411, 2011).